PSCA (prostate stem cell antigen)
Diseases named in the same sentence as PSCA in open-access papers (continued):
Sharing a sentence is not in itself a finding about the gene and the disease.
gastric cancer (continued). "Thus, we conducted a comprehensive meta-analysis to evaluate the association between the PSCA rs2976392 polymorphism and susceptibility to gastric cancer (GC)." (PMID 40741413, 2025). "Our findings underscore a significant association between specific genetic polymorphisms, such as those in the genes mucin 1 (MUC1), prostate stem cell antigen (PSCA), tumor necrosis factor-alpha (TNF-α), and an increased risk of developing gastric cancer." (PMID 39355481, 2024). "Meanwhile 22 variants were identified significantly associated with gastric cancer: 3 (PLCE1 rs2274223, PSCA rs2976392, MUC1 rs4072037) were high and 19 SNPs were intermediate level of summary evidence, respectively." (PMID 34491229, 2021). "For example, a single-nucleotide polymorphism (SNP), prostate stem cell antigen (PSCA)-rs2294008, was found to confer susceptibility to gastric cancer risk both in Japan and worldwide." (PMID 34771687, 2021). "Among them, the expression of lnc-PSCA-4:2 in blood is closely related to stage, vascular invasion and lymphatic metastasis of gastric cancer patients, and lnc-MB21D1-3:5 was significantly correlated with the differentiation degree of gastric cancer." (PMID 34295803, 2021). "Genome-Wide Association Studies (GWAS) have shown that genetic diversities MUC1 (Mucin 1) and PSCA (Prostate Stem Cell Antigen) genes are involved in gastric cancer." (PMID 32660489, 2020). "The penetrance rates of genetic polymorphisms in pro-inflammatory genes (IL1B, IL8, TNFA, etc.)and PSCA (Prostate Stem Cell Antigen) are low (probably less than 5%) for sporadic gastric cancer, which accounts for more than 90% of gastric cancer." (PMID 31035365, 2019). "Abnormal expression of PSCA has been observed in many types of human cancers, including prostate, pancreas, bladder, ovarian, esophagus, gallbladder and gastric cancer." (PMID 31416884, 2019). "Previous studies have identified the prostate stem cell antigen (PSCA) gene rs2294008 C > T and rs2976392 G > A polymorphisms to be associated with the risk of gastric cancer, the results of which are inconsistent." (PMID 31416884, 2019). "For example, among SNPs associated with increasing risk of gastric cancer (GC), PLCE1 rs2274223 has an OR of 1.57, and PSCA rs2294008 an OR of 1.33." (PMID 30597917, 2018). "The objective of this study is to investigate the role of rs2294008 and PSCA expression in the gastritis-gastric cancer carcinogenic pathway." (PMID 29423095, 2018). "SNP rs2294008 in Prostate Stem Cell Antigen (PSCA) and decreased PSCA expression are associated with gastric cancer." (PMID 29423095, 2018). "In the current hospital based case-control study, we investigated the potential associations of PSCA rs2294008 C>T and rs2976392 G>A, PLCE1 rs2274223 A>G and MUC1 rs4072037 T>C polymorphisms with stomach cancer susceptibility among a Chinese population." (PMID 25658482, 2015). "Logistic regression analysis of associations between the genotypes of PSCA, MUC1, PLCE1 and stomach cancer susceptibility in a Chinese population." (PMID 25658482, 2015). "PSCA, a prostate stem cell antigen, has been reported to be upregulated in bladder, prostate and pancreatic cancers but is downregulated in esophageal and gastric cancers." (PMID 23024765, 2012). "Two genes (PSCA and LYNX1) presented causal associations with gastric cancer." (PMID 41209561, 2025). "PSCA is one of the down-regulated genes in gastric cancer, and has a low expression level in GC, Thus PSCA is a tumor suppressor in gastric cancer and prevents cell proliferation, but its mechanism of action is unknown." (PMID 38627732, 2024). "Further investigations regarding PSCA polymorphisms and their functions are required to provide pathophysiological findings and establish reliable biomarkers, finally leading to the development of new therapeutic GMA drugs to reduce gastric cancer risk." (PMID 36010338, 2022).
gastric cancer (continued). "Therefore, this meta-analysis suggested that the PSCA rs2294008 C>T and rs2976392 G>A polymorphisms might be associated with cancer susceptibility, which might act as a potential predicted biomarker for genetic susceptibility to cancer, especially in gastric cancer and bladd er cancer." (PMID 28881685, 2017). "PSCA seems to act as an oncogene in some cancers, such as prostate, bladder, renal and ovarian carcinomas, and as a tumor suppressor in others, including esophageal and gastric cancer." (PMID 24719866, 2014). "We found that PSCA rs2294008 CT/TT, PSCA rs2976392 AG/AA and PLCE1 rs2274223 AG/GG genotypes were associated with a significantly increased stomach cancer risk in a Chinese population, whereas, the MUC1 rs4072037 T>C were associated with decreased stomach cancer susceptibility." (PMID 25658482, 2015). "In addition, PSCA is up-regulated in several solid tumors (pancreas, bladder, renal cell carcinoma and ovarian mucinous), and down-regulated in esophagus cancer, gastric cancer and gallbladder carcinoma." (PMID 26308216, 2015). "PSCA interacts with DDX5 and promotes DDX5 degradation through ubiquitination to inhibit the progression of gastric cancer." (PMID 35992805, 2022). "This can only be explained in part by the prostate stem cell antigen (PSCA), which is responsible for gastric cancer and bladder cancer at the same time because it is responsible for these two types of cancer across different ethnicities." (PMID 36466542, 2022). "The expression of lnc-PSCA-4:2 and lnc-ABCC5-2:1 in the plasma of gastric cancer patients was lower than healthy control, and lnc-MB21D1-3:5 was up-regulated in the plasma samples compared with healthy control." (PMID 34295803, 2021). "The expression of lnc-ABCC5-2:1, lnc-PSCA-4:2 and lnc-RNF135-1:3 in gastric cancer tissues was significantly lower than pericarcinomatous tissue." (PMID 34295803, 2021). "For example, a lower expression of genes that may play an important role in suppressing gastric cancer (GKN1, LIPF, ANXA10, MUC6, PSCA, and SNHG5) was found." (PMID 35625760, 2022). "Genetic variations in other genes (e.g. KDM5A, DNAH7, PLCE1, PSCA, PRKAA1, MUC1) reported to be specifically associated with gastric cancer initiation and progression were not investigated in the current study." (PMID 27929383, 2016).
bladder cancer (31 papers, 2010 to 2026). "Previous studies have demonstrated that several genetic variants of PSCA were associated with cancer susceptibility, such as rs2736098 for bladder cancer, and rs2294008 for gastric cancer." (PMID 41209561, 2025). "Among them is PSCA, the expression of which is influenced by genetic polymorphisms associated with bladder cancer risk." (PMID 31562298, 2019). "Genetically, genome-wide association studies (GWAS) have revealed that genes on chromosome 8q24, particularly the PSCA gene (Prostate Stem Cell Antigen), were associated with increased metastatic potential of bladder cancer." (PMID 31866765, 2019). "Further, we confirmed a firm association between the PSCA rs2294008 C > T polymorphism with increased susceptibility of gastric and bladder cancers, signifying PSCA rs2294008 polymorphism as potential biomarker for these cancers." (PMID 26891331, 2016). "Only one of the previous meta-analyses explored the association between polymorphisms of PSCA gene and bladder cancer, which included a total of four studies with 9617 cases and 16323 controls." (PMID 26124924, 2015). "In the literature, a GWAS revealed that PSCA gene variation confers susceptibility to urinary bladder cancer, later studies confirmed the association in specific population and analyzed the gene expression by genotypes of rs2294008." (PMID 26006239, 2015). "One such study identified a significant association between the PSCA rs2294008 (C>T) polymorphism and the risk of bladder cancer in US and European populations." (PMID 25624885, 2015). "Recently, a significant association has been identified between the PSCA rs2294008 (C>T) polymorphism and the risk of developing bladder cancer." (PMID 25624885, 2015). "Tumor suppressor and other cancer-associated genes were also identified, including TNFAIP3, SGK1, and PSCA, which have been implicated in MM or bladder cancer." (PMID 24466111, 2014). "Three previous GWAS found a significant association of the T allele of rs2294008, a functional SNP in the PSCA gene, with the risk of gastric and bladder cancers and the C allele for duodenal ulcer." (PMID 24023815, 2013). "Although PSCA is recognized as a membrane glycoprotein primarily associated with the prostate, its upregulation has also been noted in a range of malignancies, including urinary bladder cancer, renal cell carcinoma, ovarian mucinous tumor, and PDAC." (PMID 37894284, 2023). "On the contrary, the T risk allele of rs2294008 was associated with increased PSCA mRNA expression, suggesting that both variants may be important for bladder cancer susceptibility, possibly through different mechanisms." (PMID 27001215, 2016). "Moreover, the PSCA gene rs2294008 C>T polymorphism was also found to be associated with increased bladder cancer risk by a three-stage GWAS with a total of 5038 cases and 9363 controls." (PMID 26124924, 2015). "Prostate stem cell antigen (PSCA) which is overexpressed on metastatic prostate, pancreatic, and bladder cancer cells is an alternative target to PSMA." (PMID 41049848, 2025). "Moreover, genes such as NAT2, TP63, GSTM1, MYC, TACC3‐FGFR3, PSCA, CLPTM1L‐TERT, APOBEC3A‐CBX6, UGT1A, and CCNE1 get mutated in bladder cancer." (PMID 40755497, 2025). "Moreover, PSCA mRNA expression was also found to be strongly up-regulated in bladder cancer samples in comparison to adjacent normal tissue." (PMID 23752272, 2013). "Genome-wide association studies of bladder cancer identified single-nucleotide polymorphisms (SNPs) on chromosome 8q24, upstream of the MYC oncogene, on chromosome 3q28 near the TP63 tumor suppressor gene, and in the PSCA gene to be associated with bladder cancer risk." (PMID 25234557, 2014). "However, the role of PSCA in bladder cancer as well as the mechanism by which rs2294008 affects PSCA mRNA expression is unknown." (PMID 23752272, 2013).
bladder cancer (continued). "In our previous study, by using of prostate stem cell antigen enhancer (PSCAE), human bladder cancer-specific uroplakin II promoter UP II and the early adenoviral genes E1A, we constructed bladder cancer-specific oncolytic adenovirus Ad-PSCAE-UPII-E1A." (PMID 28789701, 2017). "This adenovirus is a dual specific vector which contains prostate stem cell antigen enhancer (PSCAE) and human uroplakin II (hUPII) promoter targeted bladder cancer." (PMID 28789701, 2017). "We also detected some biological markers in the diagnosis of recurrent bladder cancer was dysregulated in UCB, including KRT20 (Cytokeratin 20), BIRC5 (Survivin), CDH1 (E-cadherin) and PSCA (Prostate Stem Cell Antigen-14)." (PMID 24622401, 2014). "Prostate stem cell antigen (PSCA) is a highly glycosylated cell surface protein which is overexpressed in several malignancies including prostate, pancreas, and urinary bladder cancers." (PMID 24391668, 2013). "Prostate stem cell antigen (PSCA) is a glycosylphosphatidylinositol (GPI) anchored protein expressed not only in prostate but also in pancreas and bladder cancer as shown by immunohistochemistry and mRNA analysis." (PMID 20374648, 2010).
pancreatic cancer (29 papers, 2002 to 2025). "Prostate stem cell antigen (PSCA) is a glycosylphosphatidylinositol-linked cell surface antigen expressed in pancreatic cancers." (PMID 25935754, 2015). "HMGA2 and PSCA have been reported to be associated with pancreatic cancer." (PMID 25502777, 2014). "The expression of prostate stem cell antigen (PSCA) is specifically elevated in primary human pancreatic cancer cells compared with adjacent normal tissue." (PMID 40705122, 2025). "Functionalized InP/ZnS QDs bioconjugates are prepared by treating QD surfaces with mercaptosuccinic acid followed by bioconjugation with monoclonal antibodies specific to pancreatic cancer, i.e. anti-claudin 4 and anti-prostate stem cell antigen (anti-PSCA)." (PMID 36376956, 2022). "Abate-Daga and colleagues proposed targeting prostate stem cell antigen in a humanized mouse model of pancreatic cancer." (PMID 31936611, 2020). "An increased expression of PSCA was observed in prostatic, bladder, and pancreatic cancers, indicating its oncogenic roles in tumor development of these cancers." (PMID 29423095, 2018). "Various studies have reported the potential importance of PSCA as a cell-surface antigen in the diagnosis and treatment of prostate, bladder, gastric and pancreatic cancers." (PMID 25624885, 2015). "The results showed that overexpression of HMGA2 and PSCA was detected in 76.7% and 65.0% of pancreatic cancer patients, respectively." (PMID 25502777, 2014). "And overexpression of PSCA was significantly associated with lymph node metastasis, and overexpression of HMGA2 was significantly associated with invasive depth of pancreatic cancer." (PMID 25502777, 2014). "Further, overexpression of PSCA was significantly associated with lymph node metastasis, and overexpression of HMGA2 was significantly associated with invasive depth of pancreatic cancer." (PMID 25502777, 2014). "Antibodies, such as anti-claudin 4 and anti-prostate stem cell antigen, whose receptors are known to be upregulated in both primary and metastatic pancreatic cancers, were used as targeting agents." (PMID 25988156, 2014). "Further validation showed that overexpression of PSCA was significantly associated with lymph node metastasis, and overexpression of HMGA2 was significantly associated with invasive depth of pancreatic cancer." (PMID 25502777, 2014). "Our study revealed that gains of HMGA2 and PSCA were detected in one and four pancreatic carcinomas, respectively." (PMID 25502777, 2014). "Prostate stem cell antigen (PSCA) is a cell surface protein present in about 70% of pancreas cancers with normal tissue expression being low." (PMID 22016635, 2011). "They determined that prostate stem cell antigen was overexpressed in pancreatic cancer and confirmed this finding by subsequent RT–PCR and immunohistochemistry analyses of primary pancreatic cancer specimens." (PMID 11953821, 2002). "We determined the genes that express differently in pancreatic cancer tissues compared with normal tissues and associate with survival (P < 0.05) as Hub genes, yielding a total of six Hub genes, including S100A14, KRT8, KRT19, MAL2, MYO5B, and PSCA." (PMID 36522691, 2022). "Numerous clinical studies have identified specific targets, such as mesothelin (MSLN), CD133, Prostate stem cell antigen (PSCA), Claudin 18.2, and HER-2, for CAR-T immunotherapy in pancreatic cancer (PCA)." (PMID 38801637, 2024). "In a phase 1/2 clinical trial, treatment with prostate stem cell antigen (PSCA)-targeting and iMC-containing CAR-T cells (named BPX-601) yielded a stable disease (SD) in three out of five advanced pancreatic cancer patients (NCT02744287)." (PMID 35053463, 2022). "The target antigens in multiple early-phase CAR T-cell clinical trials for pancreatic cancer include mesothelin (MSLN), prostate stem cell antigen (PSCA), carcinoembryonic antigen (CEA), HER2, MUC1, and CD133." (PMID 36290818, 2022).
pancreatic cancer (continued). "With this in mind, an article from 2017 summarized the possible targets of CAR T-cells in pancreatic cancer and added CD24, prostate stem cell antigen, and natural killer receptors for the construction of CARs." (PMID 31936611, 2020). "Prostate stem cell antigen (PSCA) is a glycosylphosphatidylinositol (GPI)-anchored cell surface protein widely expressed in bladder, prostate, and pancreatic cancers." (PMID 32010446, 2020). "In a study conducted on pancreatic cancer models, they developed trivalent CAR T-cells that targets prostate stem cell antigen (PSA), IL-2, and transforming growth factor-B to improve CAR-T cell migration towards the cancer site and overcome the immunosuppressive environment." (PMID 39312080, 2024). "Several antigens, such as PSCA, MUC1, claudin, CEA, and carcinoembryonic antigen-related cell adhesion molecule (CEACAM7), have been discovered as potential targets for CAR-T cell treatment in pancreatic cancer." (PMID 38892913, 2024). "It was recently shown that pre-conditioning with cyclophosphamide could favorably modify the immunosuppressive TME, yielding durable curative responses of prostate stem cell antigen-targeting 4-1BB-co-stimulated CAR-T cells in metastatic prostate and pancreas cancer models." (PMID 35053463, 2022).
duodenal ulcer (9 papers, 2013 to 2022). An ulcer in the duodenal wall. "Recently we conducted the genome wide association study for duodenal ulcer and identified disease susceptibility variations at two genetic loci corresponding to the Prostate stem cell antigen (PSCA) gene and the ABO blood group (ABO) gene." (PMID 23704932, 2013). "Some single-nucleotide polymorphisms (SNPs) in the prostate stem cell antigen gene (PSCA) are associated with GC and duodenal ulcers." (PMID 36010338, 2022). "Risk alleles (C allele at rs2294008) in the two sample sets were consistent between duodenal ulcer and gastric ulcer, indicating the role of PSCA variation as common genetic factors for peptic ulcer." (PMID 23704932, 2013). "In our previous genome wide association study (GWAS) of duodenal ulcer using a total of 7,035 cases and 25,323 controls, we identified the significant association of genetic variations at PSCA (prostate stem cell antigen) and the ABO blood group with duodenal ulcer." (PMID 23704932, 2013).
prostate tumor (7 papers, 2012 to 2022). "Overexpression of PSCA was identified to be associated with prostate tumor metastasis in many studies, which makes it an ideal target for immunotherapy." (PMID 23139820, 2012). "Prostate stem-cell antigen (PSCA) is overexpressed on the surface of primary androgen independent prostate tumor cells, as well as metastases." (PMID 24213509, 2012). "Many studies have demonstrated that prostate stem cell antigen (PSCA) is an attractive target for immunotherapy based on its overexpression in prostate tumor tissue, especially in some metastatic tissues." (PMID 23139820, 2012).
breast carcinoma (6 papers, 2016 to 2024). "In this context, it was reported, for instance, that PSCA single nucleotide polymorphims (e.g. rs2294008 or rs2978974) are associated with increased risk of developing breast cancer." (PMID 28903367, 2017). "Among the many PSCA SNPs, rs2294008C > T, rs2978974G > A and rs2976392G > seem to have the highest number of breast cancer studies in the Chinese population." (PMID 38627732, 2024). "Some of these investigations have an epidemiological focus and report on genetic variation of the PSCA gene and its relation to breast cancer development." (PMID 28903367, 2017). "Several clinical trials are currently being conducted to evaluate the effectiveness of CTAs, such as NY-ESO-1, MAGE, MSLN, PRAME, PSCA, ROR2 and WT1, as treatment targets in breast cancers and other solid tumours." (PMID 34359776, 2021).